SETD1A (SET domain containing 1A, histone lysine methyltransferase)
Description:
Histone methyltransferase that catalyzes methyl group transfer from S-adenosyl-L-methionine to the epsilon-amino group of 'Lys-4' of histone H3 (H3K4) via a non-processive mechanism. Part of chromatin remodeling machinery, forms H3K4me1, H3K4me2 and H3K4me3 methylation marks at active chromatin sites where transcription and DNA repair take place. Responsible for H3K4me3 enriched promoters and transcriptional programming of inner mass stem cells and neuron progenitors during embryogenesis (By similarity). Required for H3K4me1 mark at stalled replication forks. Mediates FANCD2-dependent nucleosome remodeling and RAD51 nucleofilaments stabilization at reversed forks, protecting them from nucleolytic degradation. Does not methylate 'Lys-4' of histone H3 if the neighboring 'Lys-9' residue is already methylated. Binds RNAs involved in RNA processing and the DNA damage response.
Synonyms: KIAA0339; KMT2F; SET1; SET1A; EPEDD; EPEO2; NEDSID
Tractability: PROTAC: ubiquitination databases record sites on it; its protein half-life has been measured.
Target class: Enzyme; Transferase
Gene: Protein-coding gene on chromosome 16 (30,957,294 to 30,984,664, forward strand). Ensembl gene ENSG00000099381.
Subcellular location: Nucleus speckle; Chromosome; Cytoplasm
Subcellular location (Human Protein Atlas): Nuclear speckles
Pathways (Reactome):
Gene expression (Transcription): Formation of WDR5-containing histone-modifying complexes; RUNX1 regulates genes involved in megakaryocyte differentiation and platelet function
Chromatin organization: PKMTs methylate histone lysines
Gene Ontology:
Molecular function: beta-catenin binding; histone H3K4 methyltransferase activity; histone H3K4 monomethyltransferase activity; protein binding; RNA binding; RNA polymerase II-specific DNA-binding transcription factor binding; histone H3 methyltransferase activity; nucleic acid binding
Biological process: brain development; regulation of chromatin organization; regulation of hematopoietic stem cell differentiation; chromatin remodeling
Cellular component: chromatin; chromosome; cytoplasm; histone methyltransferase complex; nuclear speck; nucleus; Set1C/COMPASS complex; nucleoplasm
Genetic constraint (gnomAD): Loss-of-function variants: 29 observed, 141.84 expected, observed/expected ratio (o/e) 0.2, 90% interval 0.15 to 0.28. The synonymous counts are far from expectation, so gnomAD's model fits this gene poorly and the ratio says little. Missense variants: 2,103 observed, 2,345 expected, observed/expected ratio (o/e) 0.9, 90% interval 0.86 to 0.93. Synonymous variants: 1,134 observed, 963.24 expected, observed/expected ratio (o/e) 1.18, 90% interval 1.12 to 1.24.
Homologues: Orthologues: chimpanzee SETD1A (99% identical), dog SETD1A (94% identical), pig SETD1A (93% identical), guinea pig SETD1A (92% identical), rat Setd1a (91% identical), Caenorhabditis elegans met-1 (7% identical), Drosophila melanogaster G9a (7% identical), Drosophila melanogaster Set2 (5% identical), Caenorhabditis elegans set-8 (4% identical), Caenorhabditis elegans set-6 (4% identical), Caenorhabditis elegans set-21 (4% identical), Caenorhabditis elegans set-19 (4% identical), and 6 more. Paralogues in human: SETD1B (42% identical), KMT2A (19% identical), KMT2B (17% identical), KMT2C (17% identical), KMT2D (16% identical), ASH1L (10% identical), EHMT1 (8% identical), NSD1 (8% identical), EHMT2 (8% identical), NSD3 (7% identical), NSD2 (7% identical), SETBP1 (6% identical), and 7 more.
Diseases named in the same sentence as SETD1A in open-access papers:
SETD1A is named in the same sentence as 98 diseases in open-access papers, as found by Europe PMC text mining. Sharing a sentence is not in itself a finding about the gene and the disease. The quoted sentences say what the papers report.
schizophrenia (47 papers, 2017 to 2026). A major psychotic disorder characterized by abnormalities in the perception or expression of reality. "While rare de novo variants affecting individual genes have been identified to contribute to schizophrenia globally, only a single gene, SETD1A, has been robustly associated with schizophrenia, previously." (PMID 41087560, 2026). "Rare heterozygous null mutations in SETD1A, a gene encoding a key epigenetic regulatory protein, have been definitively linked to increased risk for schizophrenia and neurodevelopmental disorders." (PMID 41659667, 2026). "Rare loss-of-function variants for Setd1a have been identified as a strong risk factor for schizophrenia." (PMID 41533795, 2026). "Recent whole exome sequencing of schizophrenia cases identified loss-of-function variants in SETD1A that are associated with various neurodevelopmental disorders, including schizophrenia (SCZD; OMIM 181500)." (PMID 40469903, 2025). "For instance, ORY-1001 has shown efficacy in normalizing ASD-related and schizophrenia-related symptoms in Shank3-deficient and Setd1a-deficient mice, respectively." (PMID 40102613, 2025). "Here we show that mice with haploinsufficiency of Setd1a, a schizophrenia risk gene encoding a histone H3K4 methyltransferase, develop an enlarged DG with more dentate granule cells after young adulthood." (PMID 38971831, 2024). "Loss of function (LoF) mutations affecting the histone methyl transferase SETD1A are implicated in the aetiology of a range of neurodevelopmental disorders including schizophrenia." (PMID 39141687, 2024). "Variable expressivity and pleiotropy have previously been shown for SETD1A, as well as a set of genes implicated in monogenic syndromes, for which neurodevelopmental disorders and schizophrenia are part of the clinical spectrum." (PMID 40225914, 2024). "In humans, rare heterozygous loss-of-function variants in the Setd1a gene increase the risk of schizophrenia (SCZ) about 35-fold." (PMID 38971831, 2024). "Altered mitochondrial gene expression changes have also been observed in an RNAi SETD1A knockdown cellular model and mitochondrial dysfunction has been repeatedly implicated in the pathogenesis of schizophrenia." (PMID 39141687, 2024). "Mutations in the SETD1A gene have been associated with schizophrenia, and some have been reported to cause seizures." (PMID 37928142, 2023). "In humans, SETD1A is increasingly reported to be related to the development of schizophrenia, as several studies identified mutations in the Setd1A gene in schizophrenia patients." (PMID 38003223, 2023). "SETD1A encodes a histone methyltranferase and has previously been associated with schizophrenia, intellectual disability, and speech and/or language delays." (PMID 36117209, 2023). "Heterozygous loss-of-function mutations in SETD1A have been associated with increased risk of schizophrenia and intellectual disability." (PMID 36581615, 2022). "Recently, loss-of-function mutations in SETD1A, a histone methyltransferase, have been linked to increased schizophrenia risk and global developmental delay." (PMID 36581615, 2022). "Heterozygous loss-of-function (LoF) mutations in SETD1A, which encodes a subunit of histone H3 lysine 4 methyltransferase, cause a neurodevelopmental syndrome and increase the risk for schizophrenia." (PMID 35508131, 2022). "Haploinsufficiency of schizophrenia-associated gene Setd1a causes cell type-specific transcriptional changes in the brain." (PMID 35245111, 2022). "For example, in the initial report of a genome-wide significant association between loss-of-function variants in SETD1A and schizophrenia, 7 of 10 people with schizophrenia carrying these mutations also had learning difficulties." (PMID 34974922, 2022). "SETD1A haploinsufficiency is associated with a range of neuropsychiatric conditions including schizophrenia, epilepsy with seizures, obsessive compulsive disorder, psychotic episodes, and intellectual disability." (PMID 35439434, 2022).
schizophrenia (continued). "Loss-of-function (LoF) mutations in the gene encoding histone methyltransferase, SETD1A, confer substantial risk to schizophrenia." (PMID 35531971, 2022). "We utilized MoNNets for quantitative in vitro modelling of schizophrenia-related network dysfunctions caused by highly penetrant mutations in SETD1A and 22q11.2 risk loci." (PMID 35680927, 2022). "Recently, dominant mostly de novo variants in SETD1A have clinically been linked to developmental delay, intellectual disability (DD/ID), and schizophrenia (SCZ)." (PMID 34803610, 2021). "SETD1A variants have also been found in schizophrenia cohorts and mouse models support SETD1A involvement in schizophrenia." (PMID 34345025, 2021). "SETD1A, a lysine-methyltransferase, is a key schizophrenia susceptibility gene, and cognitive as well as circuitry deficits were observed in in Setd1a-deficient mice." (PMID 34082769, 2021). "Particularly, the mutations that modify SETD1A function were documented to contribute to neurodevelopmental disorders, including autism and schizophrenia and also to gene silencing." (PMID 29745862, 2018). "Recently, histone methylation (common variants) has been implicated as a general biological process involved in schizophrenia pathogenesis, specifically SETD1A, a component of a histone methyltransferase complex that produces H3K4me, H3K4me2 and H3K4me3." (PMID 28387726, 2017). "Extending to neuropsychiatric disorders, a recent study identified rare LoF variants in the SETD1A gene to be associated with schizophrenia." (PMID 28449691, 2017). "Setd1a may have important roles in early development, as shown in the maternal high-fat diet model in mice, a manipulation that is associated with schizophrenia-relevant phenotypes in animal models, where Setd1a expression is reduced in the placenta." (PMID 39141687, 2024). "With a literature demonstrating Setd1a as a risk candidate for a schizophrenia, we observed a number of phenotypes of relevance, including increased anxiety-related behaviour, enhanced acoustic startle response, and decreased pre-pulse inhibition of acoustic startle." (PMID 39141687, 2024). "Also, a large-scale exome sequencing study identified single genes whose rare mutations substantially increase the risk for schizophrenia, of which six genes (SETD1A, CUL1, XPO7, GRIA3, GRIN2A, and RB1CC1) showed odds ratios larger than ten." (PMID 36878965, 2023). "SETD1A, a lysine-methyltransferase (lysine-methyltransferase), has been shown to be a risk gene for schizophrenia associated with cognitive impairment, and its mutation increases the risk of schizophrenia." (PMID 36826468, 2023). "This study highlights biological pathways through which SETD1A LOF may confer risk to schizophrenia." (PMID 35531971, 2022). "To explore the biological pathways through which SETD1A contributes to risk for schizophrenia, we quantified gene expression and synaptosome composition in the frontal cortex of mice carrying a Setd1a LoF allele at multiple prenatal and postnatal stages of development." (PMID 35531971, 2022). "We hypothesized that molecular pathways disrupted by Setd1a LoF also contribute risk for schizophrenia through enrichment for genetic association with the disorder." (PMID 35531971, 2022). "As SETD1A loss-of-function mutations are associated with increased schizophrenia risk, our model may also reflect a state of increased vulnerability rather than active disease pathophysiology." (PMID 36581615, 2022). "Genetic association with schizophrenia of transcripts and proteins disrupted by Setd1a LoF." (PMID 35531971, 2022). "Moreover, SETD1A, histone methyltransferase, is one of the high-confidence schizophrenia risk genes that harbor excess of rare loss-of-function variation." (PMID 34356078, 2021). "SETD1A, which is a schizophrenia-susceptibility gene, was interestingly also found for AD." (PMID 34807913, 2021).
schizophrenia (continued). "In addition, LoF variants in SETD1A have been associated with neurodevelopmental disorders that include schizophrenia, ID and speech/language delays." (PMID 29463886, 2019). "Recent support for this comes from a recent meta‐analysis of 4,264 schizophrenia cases, 9,343 controls, and 1,077 parent‐proband trios in which genome‐wide significant support was obtained for rare loss‐of‐function SNVs in the gene SETD1A." (PMID 28719003, 2017). "According to the results, all heterozygous carriers of SETD1A are rare loss-of-function variants that satisfied the full diagnostic criteria for schizophrenia, including classic positive symptoms, and this classes SETD1A as a new gene for susceptibility to the disease." (PMID 28387726, 2017). "Taken together, these findings provide further evidence that Setd1a haploinsufficiency, early in development, may have a more generic effect on biological mechanisms, rather than specifically targeting pathways known to be implicated in schizophrenia." (PMID 39141687, 2024). "Here, we show that heterozygous disruption of SETD1A in human induced pluripotent stem cell (hiPSC)-derived neurons results in reduced neurite outgrowth and spontaneous activity, two phenotypes commonly associated with schizophrenia, as well as alterations in metabolic capacity." (PMID 36581615, 2022). "Setd1a heterozygous KO mice recapitulated several behavioral abnormalities related to schizophrenia." (PMID 41533795, 2026). "Taken together these data demonstrate that this new Setd1a LoF mouse model recapitulates some of the core findings of previous models, of relevance to neurodevelopmental disorders and schizophrenia in a large experimental cohort of both sexes." (PMID 39141687, 2024). "Sex differences in schizophrenia are well documented, in terms of incidence and symptom presentation, thus the altered developmental indices in Setd1a+/- conceptuses and behavioural differences we found add a further dimension to this theory." (PMID 39141687, 2024). "Studies of etiologically valid cellular models of schizophrenia produced with this technology, including those with 22q11.2 deletion, 16p11.2 deletion/duplication, SETD1A LOF/PTV, and NRXN LOF/PTV, have been conducted and reported." (PMID 36878965, 2023). "Rare loss-of-function (LoF) variants in the SETD1A gene, encoding SET Domain Containing 1A, confer substantial risk to schizophrenia and other neurodevelopmental disorders." (PMID 35531971, 2022). "TCF4 binding sites were also found at other schizophrenia risk loci including the nicotinic acetylcholine receptor cluster, CHRNA5/CHRNA3/CHRNB4 and SETD1A." (PMID 29228394, 2018). "In this study, we examined developmental changes in spine distribution in multiple mouse models of schizophrenia (Grin1 cKO, Hivep2 KO, and Setd1a cKO) and found that experience-dependent spine formation during adolescence, rather than pruning, was commonly affected." (PMID 41533795, 2026). "In addition to including members of the Set1-like H3K4 methyltransferase family (Kmt2a, Kmt2b, Kmt2c, and Kmt2d), these modules also encompassed rare variant genes associated with schizophrenia and ASD (Setd1a, Cacna1g, Ank3, Shank1, and Shank3)." (PMID 40102613, 2025). "Thus, we find evidence for changes in a number of phenotypes which strengthen the support for the use of Setd1a haploinsufficient mice as a model for the biological basis of schizophrenia." (PMID 39141687, 2024). "These abnormalities strengthen the support for the use of Setd1a haploinsufficient mice as a model for the biological basis of schizophrenia, although the neural mechanisms underpinning this may be complex and involve pre-natal effects." (PMID 39141687, 2024).
schizophrenia (continued). "Taken together our findings strengthen the support for the use of Setd1a haploinsufficient mice as a model for the biological basis of schizophrenia and point towards possible underpinning neural mechanisms, that may be sexually dimorphic." (PMID 39141687, 2024). "Gene-set enrichment analysis revealed that genes that were differentially expressed in Setd1a+/- E13.5 brain were not significantly enriched for schizophrenia common variant association (B = 0.004, SE = 0.088, p = 0.48)." (PMID 39141687, 2024). "While SETD1A is enriched for PTVs in both schizophrenia and developmental disorders, previous research by us and others has been underpowered to evaluate the degree to which genic pleiotropic effects across these disorders are confined to the same functional class of variant within genes." (PMID 34504065, 2021). "Genes that regulate transcriptional activity have been strongly associated with RCVs in several psychiatric disorders; for example, CHD8 and SETD1A, which are involved in chromatin remodeling, are associated with LoF variants in early-onset NDDs (ASD and DD) and schizophrenia, respectively." (PMID 32349784, 2020). "The regulatory regions reported here significantly overlap with putative modern human positively-selected regions and schizophrenia genomic loci, and control a set of genes among which we find a high number related to chromatin regulation, and most specifically the SETD1A/HMT complex." (PMID 32299352, 2020). "We similarly found no support for SETD1A which was recently found to be significantly enriched for ultra‐rare loss‐of‐function mutations in people with schizophrenia." (PMID 28719003, 2017). "Consistent with our findings, ORY-1001 has also been shown to restore H3K4me2 levels in the brains of Shank3-deficient and Setd1a-deficient mice, suggesting that normalization of reduced H3K4me2 levels may be a key mechanism by which ORY-1001 alleviates ASD- and schizophrenia-related dysfunctions." (PMID 40102613, 2025). "However, the sensorimotor gating deficits could not be rescued by haloperidol or risperidone, suggesting that these antipsychotic agents are ineffective for ameliorating schizophrenia-relevant phenotypes in Setd1a+/- mice." (PMID 39141687, 2024). "Exome sequencing studies have implicated loss of function (LoF) mutations in the SETD1A gene that increase susceptibility for a number of neurodevelopmental disorders (NDD) and conditions, including developmental delay, early-onset epilepsy, intellectual disability and schizophrenia." (PMID 39141687, 2024). "The realization of precision medicine, such as gene therapy, for specific genetic diseases frequently comorbid with schizophrenia (e.g., 22q11.2 deletion or SETD1A haploinsufficiency syndrome) leveraging the observations in studies of these models might be the achievable goal within the next decade." (PMID 36878965, 2023). "Extensive exome sequencing from over 200 patients with schizophrenia (SCZD; OMIM 181500) revealed two de novo mutations in SETD1A, which likely cause malfunction of SETD1A activity." (PMID 28665350, 2017). "Whole exome sequencing of 4264 schizophrenia patients and 1077 trios revealed three de novo loss of function mutations in SETD1A, (also known as KMT2F), which were absent in the general population." (PMID 36384485, 2022). "We also observed reduced pre-pulse inhibition of acoustic startle, a schizophrenia-relevant phenotype, in both male and female Setd1a+/- mice which could not be rescued by either drug." (PMID 39141687, 2024). "In cohorts with people with speech disorders, SETD1A haploinsufficiency therefore seems rather frequent (2 out of 123 people with CAS and 1 out of 23 people with speech delay), compared to cohorts with people with schizophrenia (10 out of 7,776) or a neurodevelopmental disorder (4 out of 11,110)." (PMID 40225914, 2024).